INS (insulin)
Diseases named in the same sentence as INS in open-access papers (continued):
Sharing a sentence is not in itself a finding about the gene and the disease.
diabetes (continued). "Scenarios testing the impact of scaling back childhood healthy weight interventions, that is, having more children entering adulthood overweight or obese, resulted in declines in insulin sensitivity across the population and therefore increasing risk of early development of diabetes mellitus." (PMID 32475837, 2020). "Supplementation of vitamin K may reduce the risk of diabetes mellitus and improve insulin sensitivity." (PMID 32824773, 2020). "Studies have demonstrated that visfatin could promote insulin and pro-inflammatory cytokines secretions, and it is a pleiotropic protein implicated in the pathophysiology of obesity, metabolic disease, diabetes and cancer." (PMID 32503436, 2020). "The identified 42 blood clinical markers included some markers previously reported to be associated with microbiome diversity such as markers for diabetes (fasting insulin, P < 10−12), inflammation (hs-CRP, P < 10−14), liver function (ALAT, P < 10−9), and cholesterol (LDL, P < 10−16)." (PMID 33060586, 2020). "This change in the type of action may be a consequence of several factors associated with diabetes such as insulin sensitivity, immune activity, obesity, physical activity, or diet." (PMID 33202729, 2020). "Dietary factors that affect insulin demand might enhance the risk of diabetes associated with CDKAL1 variants." (PMID 32764395, 2020). "To determine whether the reduced food intake shown by Pdk2-deficient mice following diabetes is due to changes in systemic insulin or leptin levels, we collected plasma from WT and Pdk2 KO mice at 3 weeks post-STZ injection." (PMID 33219201, 2020). "Furthermore, elevated levels of some neprilysin substrates (glucagon and insulin) have been described as the main cause of diabetes, and one of the symptoms associated with sickle cell disease (substance P)." (PMID 32366041, 2020). "For instance, previous studies have consistently reported that level of serum anti-inflammatory cytokine IL-10 is significantly associated with insulin sensitivity in young individuals, which may later develop towards type 2 diabetes mellitus or chronic pain." (PMID 31991875, 2020). "The results suggested that the exercise training against diabetes-induced hyperglycemia could be associated with an increase in insulin levels, a decrease in blood glucose, and adjustment of NRG1 and ErbB2 proteins." (PMID 32509881, 2020). "Nevertheless, greater caution should be exercised when insulin is administered to elderly patients with diabetes as they may be more susceptible to hypoglycaemia." (PMID 32290465, 2020). "Impaired insulin signaling and diabetes have been extensively implicated in the pathogenesis of AD." (PMID 32192109, 2020). "A non-Euro Caucasian origin (3.08 [1.37–6.93]), previous delivery of a LGA infant (3.21 [1.31–7.87]), institution of treatment after 32 weeks of gestation (3.92 [1.86–8.25]), and insulin therapy (2.91 [1.20–7.03]) were associated with failure of diabetes management." (PMID 32346630, 2020). "Type 2 diabetes mellitus (T2DM) may result from insulin resistance or insufficient insulin secretion, which causes inefficient absorption of ingested carbohydrates by the skeletal muscle or liver, resulting in increased blood glucose levels." (PMID 33315940, 2020). "Diabetes mellitus is a metabolic condition caused by dysfunction in insulin secretion." (PMID 33204285, 2020). "Insulin treatment is recommended for older persons with diabetes who have persistent hyperglycaemia despite taking oral hypoglycaemic agents, or have A1C 7.0% or greater after maximum or combined use of such agents." (PMID 32257276, 2020). "As an association between centenarian age and insulin sensitivity has been reported, and centenarian have a very low prevalence of diabetes and obesity, centenarians may exhibit resistance against Angptl2-mediated proinflammatory processes." (PMID 32732919, 2020).
diabetes (continued). "This is because of the unavailability, or high cost, of diagnostic tests and diabetes monitoring, including HbA1c, glucose-lowering drugs, and insulin, as well as poorly trained medical doctors and paramedics, and poor compliance with the therapy and follow-up." (PMID 32098332, 2020). "Several studies have suggested that drug resistance in colon cancer patients with diabetes may be associated with long‐term insulin administration, which in turn decreases the survival rate." (PMID 32248666, 2020). "If a bias were to follow the trend from the association of MPV with diabetes, we reasoned Insulin-dependent diabetes rates may be much higher in male cases whereas females may more often be taking Metformin and sulphonylureas." (PMID 32754618, 2020). "Obesity is associated with resistance to the effects of insulin on peripheral glucose and fatty acid utilization, so-called insulin resistance, and may also lead to type 2 diabetes mellitus and contribute to the development of steatosis." (PMID 33204256, 2020). "Diabetes mellitus (DM) is caused by insufficient insulin function [...]." (PMID 33255837, 2020). "Basal–bolus insulin therapy is recommended as insulin therapy for non‐ICU hospitalized patients with diabetes, although this treatment method might increase the risk of hypoglycemia compared with SSI therapy." (PMID 31168938, 2020). "Although the weight gain commonly seen after smoking cessation may explain such a high risk of diabetes, this interruption in a short period of time can also decrease insulin sensitivity and signaling." (PMID 32906612, 2020). "Tumors linked to diabetes may secrete cytokines, especially those that secrete large amounts of interleukin-6, which is associated with insulin resistance and inflammatory signaling throughout the body." (PMID 32528752, 2020). "We firstly aimed to determine whether expression of the most abundantly-expressed islet circRNAs were associated with insulin secretory index (SI), donor HbA1c or donor diabetes status in human primary islets." (PMID 32312268, 2020). "Recently, it has been reported that patients with GS may be at an increased risk for developing T2DM, which is a type of diabetes due to a progressive loss of β-cell insulin secretion, frequently caused by insulin resistance." (PMID 32702863, 2020). "HDAC inhibition has been associated with insulin gene regulation, β-cell proliferation, and differentiation, as well as the protection of beta cells from apoptosis, thereby counteracting the effects of diabetes." (PMID 33072796, 2020). "Since hyperglycemia can trigger increased ROS and is a major cause of clinical complications associated with diabetes and obesity, the results presented have implications for those cancers associated with diabetes and for the non–insulin-dependent response of cells to high glucose." (PMID 32603375, 2020). "Diabetes is a disease of hyperglycemia caused by deficient insulin production and action." (PMID 33178692, 2020). "Some of the available drugs reduce the risk of diabetes-associated complications in the mechanisms other than those associated with lowering glycemia, while others can even delay the onset of diabetes by slowing the progressive decline in insulin secretion." (PMID 32397353, 2020). "More recent findings suggested that there might also be a hormonal component (consistent with the gender difference) resulting in decreased insulin sensitivity and subsequently an increased risk of diabetes, one of the main risk factors for PDAC." (PMID 33114159, 2020). "Insulin sensitivity could be more accurately studied with participants at risk of developing diabetes to study any long-term effects on glycaemic control." (PMID 33102510, 2020).
diabetes (continued). "In general, the incidence of TBIRS is higher in middle-aged individuals, particularly those who were African American and female, with associated or hidden autoimmune diseases, who developed diabetes with a need for very high doses of insulin and glycemia which was difficult to control." (PMID 32813762, 2020). "The hormone insulin has a central role in the regulation of blood glucose, and the main causes of diabetes are loss of insulin-producing beta cells (type I diabetes) and peripheral insulin resistance, whereby beta cells fail to meet the required insulin demand (type II diabetes)." (PMID 33158929, 2020). "In a Mendelian randomization analysis, single nucleotide polymorphisms associated with diabetes (49 variants), fasting glucose (36 variants), fasting insulin (18 variants), and early insulin secretion (17 variants) were used to examine the association with the risk of EC." (PMID 32842547, 2020). "Multivariate IPTW Cox survival analysis (Concordance statistic (95%CI): 0.80 (0.78–0.82)) shows that type of surgery, diabetes duration, baseline insulin treatment, baseline HbA1c and percentage of weight loss at 1 year were independent factors associated to diabetes remission along the follow-up." (PMID 32283783, 2020). "Diabetes Mellitus (DM) is a group of metabolic disorders characterized by a high blood sugar level over a prolonged period of time and caused by either from deficiency in insulin secretion, decreased insulin action or both." (PMID 33170888, 2020). "Studies have suggested that circulating concentrations of vitamin D may be inversely associated with the risk of diabetes, metabolic syndrome, insulin secretion, and insulin resistance." (PMID 32407388, 2020). "There are two broad etiopathogenetic categories of diabetes: type 1 diabetes (T1D), which results from absolute insulin deficiency, and T2D, which is caused by a combination of insulin resistance and inadequate insulin secreting compensation." (PMID 32371554, 2020). "Diabetes mellitus (DM) is a metabolic disorder which is characterized by increased blood glucose level with disturbances of carbohydrate, fat and protein metabolism resulting from either loss of insulin producing cells, insufficient insulin action, or both." (PMID 32214398, 2020). "Since activation of the sympathetic nervous system is associated with both impaired insulin secretion and insulin resistance, or namely with diabetes, evaluation of such activation in ordinary clinical settings may be important." (PMID 32053635, 2020). "This causes reduced insulin secretion by β-cells, which in turn leads to diabetes." (PMID 32195947, 2020). "Indirectly, by promoting the synthesis and binding of insulin (thereby decreasing insulin resistance and the risk of diabetes), vitamin D may also reduce the risk of PDAC." (PMID 33114159, 2020). "One of the postulated hypotheses is the alteration of insulin signaling which has been linked to diabetes and neurodegenerative disease development." (PMID 33374507, 2020). "Diabetes mellitus (DM) is a group of metabolic disorders characterized by hyperglycemia (elevated levels of blood sugar over a prolonged period), which results from deficiency or ineffectiveness of insulin." (PMID 32575461, 2020). "Moreover, population-based diabetes screening was associated with less need for insulin therapy after ten years and slightly better long-term glycaemic control compared to patients diagnosed during usual care." (PMID 33105611, 2020). "The effect of insulin therapy on perioperative production of ROS may be influenced by various factors including the cause of diabetes." (PMID 32993618, 2020). "Insulin underdosing increases the risk of hyperglycemia, i.e., BG concentration >180 mg/dL, which if prolonged may lead to the incidence of diabetes-related complications, such as nephropathy, retinopathy, cardiovascular diseases and neuropathy." (PMID 32664432, 2020).
diabetes (continued). "It is characterized by impaired insulin secretion, glucose intolerance, and hyperglycemia." (PMID 33569378, 2020). "It is commonly accepted that insulin hyper-secretion is considered a triggering cause of diabetes, and the discovery of the causes that are linked to insulin hyper-secretion is fundamental in the design of specific diabetes treatment." (PMID 32168836, 2020). "Collectively, insulin resistance and diabetes are associated with profound alterations in cellular glucose transport, but the cause and consequence of impaired insulin-stimulated glucose transport in the pathogenesis of the disease remains to be further investigated." (PMID 32591906, 2020). "Diabetes mellitus is referred as common metabolic abnormalities characterized as hyperglycemia, mainly caused due to insufficient production of insulin at cellular level or/and defects in insulin action." (PMID 33118125, 2020). "The strong increase in MPV associated with insulin therapy may be explained by the fact that patients with insulin-treated diabetes are likely to be at a more advanced stage of insulin resistance." (PMID 32754618, 2020). "Contrary to negative correlation, most TSGs that positively correlated with promoter methylation were not functionally enriched in the GSEA, although some of them, such as IGFBP2, had associations with diabetes, insulin resistance, insulin sensitivity, and obesity." (PMID 32709145, 2020). "Also, diabetes-specific risk factors such as diabetes duration, peripheral neuropathy, blood glucose, and insulin therapy are associated with the development of LEAD7." (PMID 32081869, 2020). "Hypoglycemic events may occur, however, when GLP-1RA are given in conjunction with diabetes medications known to cause hypoglycemia, such as basal insulin or sulfonylureas." (PMID 32308645, 2020). "As diabetes progresses, increased IL1β expression was linked to insulin resistance and beta cell destruction; with damaged beta cells eventually failing to respond to increasing insulin demand, due their rapid death and functional impairment." (PMID 33182622, 2020). "Abnormal serum calcium levels may affect insulin sensitivity and insulin release, which in turn leads to an increase in the risk of diabetes and MetS." (PMID 33382832, 2020). "To determine whether diabetes in Irp2−/− mice is caused by insulin insufficiency, we measured plasma insulin levels after intraperitoneal glucose injection." (PMID 31941883, 2020). "Inhaled insulin administration could substantially improve the quality of life for people with diabetes by overcoming the burdens and perceptions associated with the traditionally administered subcutaneous insulin." (PMID 32785196, 2020). "As high postprandial glucose and insulin levels have been associated with an increased risk of cardiovascular diseases in healthy individuals and in patients with diabetes, we conclude that rapeseed protein had a more favorable health impact on postprandial glucose metabolism than soy protein." (PMID 32751170, 2020). "The systemic metabolic alterations caused by reduced insulin secretion, in type 1 diabetes mellitus (T1DM), or progressive insulin resistance, in type 2 diabetes mellitus (T2DM), constitute continuous cardiac stress that leads to the activation of numerous cellular responses." (PMID 33195472, 2020). "As such, STZ treatment may mimic primary pathophysiological features of human diabetes including pancreatic β-cell destruction, decreased insulin production, hyperglycemia, body weight loss, and other diabetes-induced complications." (PMID 32999405, 2020). "Could abnormal insulin signaling in olfactory neurons of diabetics exacerbate SARS-CoV-2-mediated mechanisms and lead to loss in smell in Covid-19 patients?" (PMID 33328942, 2020).
diabetes (continued). "Collectively, these findings suggest that the loss of β-cell identity manifested by a dramatic reduction in insulin expression together with a dysfunctional secretory response precedes overall endocrine cell loss and is responsible for the switch to full diabetes development in our model system." (PMID 31682591, 2020). "Also, the immune function of patients with diabetes is reduced, the internal environment is disordered, and chronic inflammation and the use of drugs such as sulfonylurea, metformin, and insulin also increase the risk of gastric cancer." (PMID 32655638, 2020). "Type 2 diabetes mellitus is a chronic metabolic disorder, characterized by hyperglycemia caused by the dysregulation of blood glucose homeostasis, increased liver glucose production, insulin secretion, insulin resistance and β-cell dysfunction." (PMID 32977609, 2020). "Direct costs – diabetes-associated costs: Associated healthcare costs were assessed as excess costs by three studies, ranging between €1958.33 for patients newly treated for type 2 diabetes and €4050.45 for patients treated with insulin." (PMID 33198734, 2020). "Furthermore, a previous study showed that IGF-1 causes insulin activity and peripheral glucose utilizations to increase, hepatic glucose production to decrease, and lipid profiles in diabetes patients to improve." (PMID 33905470, 2020). "Our data also suggest that TCDD exposure alone may be insufficient to cause diabetes but could influence diabetes susceptibility in both males and females, at least in part by altering insulin secretion and/or causing irreversible beta cell death." (PMID 31996693, 2020). "High glycemic index and glycemic load from sugar-sweetened beverages might stimulate postprandial glucose and/or insulin response, which is associated with diabetes-related cancer risk." (PMID 32340309, 2020). "Many incorrect responses were submitted regarding the assumed consumption of sweet foods as a cause of diabetes (80.2%), diabetes caused by kidney failure (81.1%), the kidney as a source of insulin (81.1%) and shaking and sweating as a sign of high blood sugar (71.2%)." (PMID 32952842, 2020). "HP:0000819 Diabetes mellitus: As expected, “HP:0000819 Diabetes mellitus” is associated with different elements of diabetes, kidneys, weight, insulin, the gastrointestinal tract, livers, and the cardiovascular system, further validating the methodology and pipeline." (PMID 32459809, 2020). "Moreover, while global knockout of Scd1 in mice improves insulin sensitivity, when introduced on the ob/ob background with leptin-deficiency, Scd1 deletion leads to a worsening of diabetes." (PMID 31796987, 2020). "The implication of RAS was confirmed by the successful therapeutic use of RAS inhibitors and RAS receptor blockers in inhibiting the onset of diabetes complications, and also enhancing insulin sensitivity associated with decreased adipocyte size and increasing transcapillary glucose transport." (PMID 33240326, 2020). "This inhibition has a long-term relation in the management of diabetes as compared to comparable with the drug acarbose, which upon high concentration caused pancreatic exhaustion, insulin resistance, glucose intolerance and an increased insulin demand." (PMID 32971839, 2020). "In conclusion, this cross-sectional study showed that patients with T2DM in Kuwait have a high prevalence of depression and this was associated with worse diabetes outcomes and that insulin therapy appears to confound the association between depression and glycaemic control." (PMID 32566681, 2020). "Our objective was to observe the changes of lipid metabolism, blood glucose level and insulin sensitivity in patients with Type-2 diabetes after progressive weight loss of their body weight, so as to lay a theoretical foundation for diabetes treatment and education in the future." (PMID 33235568, 2020).